NAGS (N-acetylglutamate synthase)
Description:
Plays a role in the regulation of ureagenesis by producing the essential cofactor N-acetylglutamate (NAG), thus modulating carbamoylphosphate synthase I (CPS1) activity.
Synonyms: AGAS; ARGA; NAT7
Tractability: Small molecule: a structure with a bound ligand is known. PROTAC: ubiquitination databases record sites on it; its protein half-life has been measured.
Gene: Protein-coding gene on chromosome 17 (44,004,581 to 44,011,028, forward strand). Ensembl gene ENSG00000161653.
Subcellular location: Mitochondrion matrix
Subcellular location (Human Protein Atlas): Mitochondria
Pathways (Reactome):
Disease: NAGS variants cause NAGS deficiency
Metabolism: Urea cycle
Gene Ontology:
Molecular function: L-glutamate N-acetyltransferase activity; acyltransferase activity, transferring groups other than amino-acyl groups
Biological process: intracellular glutamate homeostasis; urea cycle; glutamate metabolic process; L-arginine biosynthetic process
Cellular component: mitochondrion; mitochondrial matrix
Genetic constraint (gnomAD): Loss-of-function variants: 34 observed, 38.42 expected, observed/expected ratio (o/e) 0.88, 90% interval 0.67 to 1.18. The upper end of that interval is the gene's LOEUF score, 1.18, which puts it in group 5 of 6, group 1 being the genes least tolerant of losing a copy. Missense variants: 665 observed, 665.77 expected, observed/expected ratio (o/e) 1, 90% interval 0.94 to 1.07. Synonymous variants: 334 observed, 302.4 expected, observed/expected ratio (o/e) 1.1, 90% interval 1.01 to 1.21.
Gene-disease validity (ClinGen):
ClinGen rates the evidence that NAGS causes each of these diseases.
hyperammonemia due to N-acetylglutamate synthase deficiency (autosomal recessive): Definitive. N-acetylglutamate synthase (NAGS) deficiency is a urea cycle disorder leading to hyperammonaemia.
Homologues: Orthologues: chimpanzee NAGS (99% identical), macaque NAGS (97% identical), dog NAGS (88% identical), rabbit NAGS (86% identical), rat Nags (86% identical), mouse Nags (86% identical), guinea pig NAGS (68% identical), pig NAGS (67% identical), tropical clawed frog nags (55% identical), zebrafish nags (46% identical).
Diseases named in the same sentence as NAGS in open-access papers:
NAGS is named in the same sentence as 50 diseases in open-access papers, as found by Europe PMC text mining. Sharing a sentence is not in itself a finding about the gene and the disease. The quoted sentences say what the papers report.
Hyperammonemia (19 papers, 2013 to 2025). An increased concentration of ammonia in the blood. "This mitochondrial disorder shares several clinical features with UCDs, particularly carbamoylphosphate synthetase 1 (CPS1) deficiency and N-acetylglutamate synthase (NAGS) deficiency, most notably the presence of hyperammonemia." (PMID 40862046, 2025). "A deficiencyof N-acetylglutamate synthase or N-acetylglutamateitself causes disturbances in the urea cycle and accumulationof free ammonium ions in the blood – hyperammonemia." (PMID 38952704, 2024). "We identified two novel variants in the NAGS gene of a female patient presenting with hyperammonemia after the delivery of her first child." (PMID 37927481, 2023). "NAGS deficiency should be considered in the differential of unexplained cases of hyperammonemia in adults as late‐onset presentation is possible, and a safe and effective therapy is available in the form of carglumic acid." (PMID 37927481, 2023). "Here we present a previously healthy 29‐year‐old female with two novel variants in the NAGS gene, diagnosed with NAGS deficiency after an episode of hyperammonemia in the postpartum period." (PMID 37927481, 2023). "In the USA, carglumic acid is approved for the treatment of acute and chronic hyperammonemia due to NAGS deficiency." (PMID 34635114, 2021). "N-acetyl glutamate synthase (NAGS) deficiency is an autosomal recessive disease that usually presents as neonatal onset life-threatening hyperammonemia." (PMID 32021803, 2020). "N-acetyl glutamate synthase (NAGS) deficiency is the rarest urea cycle defect presenting as neonatal onset life-threatening hyperammonemia." (PMID 32021803, 2020). "NAGS deficiency is clinically characterized by seizures, poor feeding, hyperammonemia, coma, and chronic headaches." (PMID 27051561, 2016). "We used adeno associated virus (AAV) based gene transfer to correct NAGS deficiency in the Nags−/− mice, established the dose of the vector needed to rescue Nags−/− mice from hyperammonemia and measured expression levels of Nags mRNA and NAGS protein in the livers of rescued animals." (PMID 33574402, 2021). "In rare circumstances, hyperammonemia can be recurrent and devastating, especially in patients with an underlying N-acetyl glutamate synthase (NAGS) deficiency, as the valproic acid can enhance this enzyme deficiency and inhibit the conversion of ammonia into urea in the liver." (PMID 30443462, 2018). "A chain of events can be traced from the primary metabolic defect to hyperammonemia: gene mutation and enzyme deficiency of HL, abnormal levels of biologically active acyl-CoAs and an acyl-CoA-dependent inhibition of N-acetylglutamate synthase, resulting in hyperammonemia." (PMID 23861731, 2013). "Laboratory findings include metabolic acidosis with anion gap, hyperammonemia due to N-acetylglutamate synthase (NAGS) inhibition, elevated plasma levels of isovalerylcarnitine, and increased urinary excretion of isovalerylglycine." (PMID 40710547, 2025). "It has been posited that the inhibitory effect of propionyl-CoA on NAGS enzyme contributes to the pathophysiology of hyperammonemia." (PMID 40710547, 2025). "The consequent accumulation of methylmalonic-CoA results in the competitive inhibition of N-acetylglutamate synthase and carbamoyl phosphate synthase 1 (CPS 1), an enzyme involved in the first and rate-limiting step of the urea cycle, causing hyperammonemia." (PMID 35652051, 2022). "The accumulation of propionyl-CoA or methylmalonyl-CoA results in the competitive inhibition of N-acetyl glutamate synthase (NAGS) and carbamoylphosphate synthase, causing a disruption in the urea cycle and consequently inducing hyperammonemia." (PMID 34635114, 2021). "N-Acetylglutamate synthase (NAGS) deficiency is an extremely rare autosomal recessive metabolic disorder affecting the urea cycle, leading to episodes of hyperammonemia which can cause significant morbidity and mortality." (PMID 33036647, 2020).
Hyperammonemia (continued). "Propionic acidemia (PA) and methylmalonic acidemia (MMA) are rare autosomal recessive inborn errors of metabolism characterized by hyperammonemia due to N-acetylglutamate synthase (NAGS) dysfunction." (PMID 31196016, 2019). "Traditionally, the hyperammonemia in organic acidemias has been thought to arise from inhibition of N-acetylglutamate synthase but may also arise from insufficiency of Krebs cycle intermediates, favoring α-ketoglutarate production from glutamate." (PMID 36771238, 2023). "Since propionyl-CoA can inhibit NAGS, the urea cycle is slowed, which leads to hyperammonemia." (PMID 35736461, 2022). "Severe NAGS deficiencies entailing the complete lack of the enzyme lead to severe neonatal hyperammonemia; late-onset presentations related to a partial lack of the enzyme have been reported in infancy, childhood, and adulthood." (PMID 32021803, 2020). "For example, a defect of N-acetylglutamate synthase (NAGS), which produces N-acetylglutamic acid (NAcGlu), induces hyperammonemia as CPS activity is allosterically regulated by NAcGlu, a product of NAGS." (PMID 35736461, 2022).
urea cycle disorder (12 papers, 2012 to 2025). A genetic inborn error of metabolism characterized by the deficiency of one of the enzymes necessary for the urea cycle. "NAGS deficiency should be considered within the differential diagnosis for patients with 3‐MGA where a proximal urea cycle disorder is suspected; a trial of carglumic acid should be initiated if active management is being pursued." (PMID 36101823, 2022). "Next generation sequencing of genes associated with urea cycle disorders identified bi‐allelic pathogenic variants in NAGS (c.622C > T|p.Arg208* and c.1368_1369delinsT|p.Gly457Alafs*110), consistent with NAGS deficiency." (PMID 36101823, 2022). "NAGS deficiency is the rarest of the urea cycle disorders, with only approximately 100 cases reported to‐date." (PMID 36101823, 2022). "Urea cycle disorders are attributed to a deficiency in N-acetylglutamate synthase, which can be successfully treated with NCG and arginine hydrochloride." (PMID 30186602, 2018). "First recognized in 1981, genetic mutations of NAGS are the rarest of the urea cycle disorders." (PMID 41002957, 2025). "Inherited N-acetylglutamate synthase deficiency (NAGSD, #237310) is an extremely rare urea cycle disorder (UCD) (estimated incidence: less than 1:2,000,000) caused by recessive mutations in the NAGS gene." (PMID 29364180, 2018). "Unlike the other urea cycle disorders, a specific pharmacological treatment for NAGS deficiency exists in the form of carglumic acid, an analog of NAG." (PMID 37927481, 2023). "A similar case occurs in the gene NAGS, which is part of the KICH model and is related to an autosomal recessive urea cycle disorder." (PMID 25578962, 2015). "CPS1, carbamoyl phosphate synthetase 1; NAGS, N-acetylglutamate synthase; ORNT1, ornithine translocase; OTC, ornithine transcarbamylase; UCD, urea cycle disorders." (PMID 37480106, 2023).
N-acetylglutamate synthase deficiency (4 papers, 2018 to 2025). "In total, 5 patients died in the neonatal period (one LCHAD deficiency, one N-acetyl-glutamate synthase (NAGS) deficiency, one type 1 citrullinemia, two non-ketotic hyperglycinemia) and 2 died later before 2 years of age (mitochondriopathies)." (PMID 31575911, 2019). "N-acetylglutamate synthase deficiency (NAGSD, MIM #237310) is an autosomal recessive disorder of the urea cycle that results from absent or decreased production of N-acetylglutamate (NAG) due to either decreased NAGS gene expression or defective NAGS enzyme." (PMID 30337552, 2018).
citrin deficiency (2 papers, 2018 to 2025). "Enzyme defects include deficiency of carbamylphosphate synthase, N-acetylglutamate synthase, ornithine transcarbamylase, argininosuccinate lyase and arginase, transporter defects are citrin deficiency and HHH-syndrome." (PMID 40285952, 2025).
non-small cell lung carcinoma (2 papers, 2014 to 2023). A group of at least three distinct histological types of lung cancer, including non-small cell squamous cell carcinoma, adenocarcinoma, and large cell carcinoma. "The NAGS protein is expressed in two cell lines commonly used to model non-small cell lung carcinoma; this provides a molecular mechanism for CPS1 activity and increased production of CP in the two cell lines." (PMID 37047726, 2023).
organic acidemias (2 papers, 2023 to 2025). "These include organic acidemias, in which high concentrations of organic acids inhibit the critical urea cycle enzyme N‐acetylglutamate synthase (NAGS), and fatty acid oxidation disorders, which cause decreased levels of acetyl‐CoA, one of the substrates of NAGS." (PMID 41163474, 2025).
adenoma (1 paper, 2024). A neoplasm arising from the epithelium. "The comparative analysis of the transcriptional profiles of NAGs and ACAs revealed the overexpression of specific genes in all adenomas compared to normal adrenals, including IGF2R, GAS2 and SLBP." (PMID 39167619, 2024).
breast carcinoma (1 paper, 2024). "N-Acetylglutamate synthase was recognized as a risk factor causally linked to ER+ breast cancer (IVW, p=0.025, OR = 1.060, 95% CI: 1.008–1.116)." (PMID 39742384, 2024). "Moreover, the analysis revealed that N-acetylglutamate synthase is causally associated with ER+ breast cancer, identified as a risk factor (IVW, p=0.025, OR = 1.060, 95% CI: 1.008–1.116)." (PMID 39742384, 2024).
carnitine deficiency (1 paper, 2022). "VPA is metabolised in the mitochondria to valproyl-coenzyme A, which inhibits N-acetylglutamate synthase, thereby limiting detoxification of ammonia to carbamoyl phosphate and also resulting in secondary carnitine deficiency." (PMID 35907043, 2022).
cerebral aneurysms (1 paper, 2024). "NAGS may influence the occurrence and development of cerebral aneurysms through the urea cycle metabolic pathway, and all of this needs further mechanistic research for validation in the future." (PMID 39087007, 2024). "The results suggest that CCDC90B, tRNA PusA, and MRM3 may be common risk factors for cerebral aneurysms (ruptured and unruptured), while AIF1 and NAGS are specifically associated with an increased risk of aSAH, unrelated to uIA." (PMID 39087007, 2024). "Overall, our findings suggest that CCDC90B, tRNA PusA, and MRM3 may be common risk factors for cerebral aneurysms (ruptured and unruptured), while AIF1 and NAGS are specifically associated with an increased risk of aSAH, unrelated to uIA." (PMID 39087007, 2024).
Deficiency (1 paper, 2023). "Family consanguinity was reported in 11 patients overall (13.9%; in 2 patients with OTC Deficiency, 4 patients with CPS1 Deficiency, 4 patients with NAGS Deficiency and 1 patient with ORNT1 Deficiency)." (PMID 37480106, 2023).
developmental arrest (1 paper, 2014). "It seems as if the expression of CPS1, OTC, ASL, NAGS and GLUD1 in dogs with CPSS has come to a developmental arrest which prevented them to normalize after closure of the shunt." (PMID 24945279, 2014).
esophagus carcinoma (1 paper, 2023). "NAGS and CPS1 genes were markedly overexpressed in esophageal carcinoma and kidney chromophobe samples, respectively." (PMID 37047726, 2023). "This suggests markedly lower NAGS and CPS1 expression in glioblastoma multiforme, glioma, lung adenocarcinoma, stomach adenocarcinoma, and stomach and esophageal carcinoma than in the liver and small intestine." (PMID 37047726, 2023). "The median NAGS, CPS1, and citrin expression was between 1.4- and 4-fold higher in glioblastoma multiforme (GBM, n = 166), glioma (GBMLGG, n = 696), stomach adenocarcinoma (STAD, n = 415), and stomach and esophageal carcinoma (STES, n = 600)." (PMID 37047726, 2023). "Therefore, we evaluated the NAGS, CPS1, and citrin mRNA and protein expression in glioblastoma multiforme, glioma, lung adenocarcinoma, stomach adenocarcinoma, and stomach and esophageal carcinoma in comparison to the expression of the three genes in the liver and small intestine." (PMID 37047726, 2023). "This hypothesis could be tested with expression constructs in which NAGS, CPS1, or citrin promoters and enhancers control reporter gene expression in cell lines that model glioblastoma, glioblastoma multiforme, stomach adenocarcinoma, and stomach and esophagus carcinoma." (PMID 37047726, 2023).
glioblastoma (1 paper, 2023). The most malignant astrocytic tumor (WHO grade IV). "The highest NAGS mRNA expression was associated with a worse outcome, i.e., shorter survival time, in patients with glioblastoma." (PMID 37047726, 2023). "However, the fraction of glioblastoma, glioblastoma multiforme, lung adenocarcinoma, and stomach adenocarcinoma samples with sequence variants in NAGS, CPS1, and citrin was low." (PMID 37047726, 2023). "High NAGS expression was associated with an unfavorable outcome in patients with glioblastoma and GBM." (PMID 37047726, 2023). "The remaining glioblastoma multiforme samples exhibited either shallow deletions or gains of the NAGS and CPS1 genes, and either gains or amplifications of the citrin gene." (PMID 37047726, 2023). "There was a trend (p = 0.07) towards a worse outcome (shorter survival time) for patients with glioblastoma multiforme exhibiting the highest expression of NAGS mRNA, compared to glioblastoma multiforme patients exhibiting the lowest expression of NAGS mRNA." (PMID 37047726, 2023). "The majority of glioblastoma multiforme samples were diploid for NAGS and CPS1 loci and exhibited gains of the citrin gene." (PMID 37047726, 2023). "NAGS and CPS1 loci were diploid in the 82 and 89%, respectively, of glioblastoma samples while 5–10% of glioblastoma samples exhibited either shallow deletions or gains of NAGS and CPS1 genes." (PMID 37047726, 2023). "Aberrant overexpression of NAGS could contribute to poor outcomes for patients with glioblastoma and glioblastoma multiforme independently of CPS1." (PMID 37047726, 2023). "Glioblastoma and glioblastoma multiforme had similar patterns of NAGS, CPS1, and citrin CNV." (PMID 37047726, 2023). "Therefore, we queried cBioPortal for the association between NAGS, CPS1, and citrin mRNA expression levels and outcomes of patients with glioblastoma, glioblastoma multiforme, lung adenocarcinoma, and stomach adenocarcinoma." (PMID 37047726, 2023). "Therefore, we examined whether individual glioblastoma, glioblastoma multiforme, lung adenocarcinoma, and stomach adenocarcinoma samples exhibit the overexpression of NAGS, CPS1, and citrin mRNA." (PMID 37047726, 2023). "The correlation between NAGS, CPS1, and citrin mRNA expression in the individual glioblastoma, GBM, LUAD, and STAD samples was very weak." (PMID 37047726, 2023). "Median expression of NAGS, CPS1, and citrin mRNA was higher in glioblastoma multiforme (GBM), glioma, and stomach adenocarcinoma (STAD) samples compared to the matched normal tissue." (PMID 37047726, 2023). "We queried the cBioPortal database to determine whether the expression of NAGS, CPS1, and citrin in glioblastoma multiforme, glioma, stomach adenocarcinoma, and lung adenocarcinoma correlated with the patient outcomes for these four tumor types." (PMID 37047726, 2023).
intrahepatic cholangiocarcinoma (1 paper, 2022). A carcinoma that arises from the intrahepatic bile duct epithelium in any site of the intrahepatic biliary tree. "In NSCLC and intrahepatic cholangiocarcinoma of the liver cancer, the mitochondrial urea cycle enzyme CPS1 was downregulated either directly or via reduced expression of NAGS, the enzyme that produces its essential cofactor N-acetylglutamate, respectively." (PMID 35838048, 2022).
lactic acidosis (1 paper, 2025). Metabolic acidosis characterized by the accumulation of lactate in the body. "For instance, CPS1 or NAGS deficiency typically lacks the pronounced lactic acidosis and ketosis observed in CA-VA deficiency." (PMID 40862046, 2025).
lung adenocarcinoma (1 paper, 2023). A carcinoma that arises from the lung and is characterized by the presence of malignant glandular epithelial cells. "There was a trend towards a worse outcome (p = 0.07) in patients exhibiting the lowest quartile of NAGS mRNA expression in lung adenocarcinoma, while the outcome was worse for patients with the highest CPS1 mRNA expression in lung adenocarcinoma." (PMID 37047726, 2023). "More than 90% of the lung adenocarcinoma samples were diploid for NAGS, CPS1, and citrin genes." (PMID 37047726, 2023). "However, the association between lower NAGS expression and unfavorable outcomes in patients with lung adenocarcinoma is consistent with the absence of correlated NAGS and CPS1 expression in this tumor type." (PMID 37047726, 2023). "Histone modifications, CTCF, and RNA polymerase II binding to NAGS, CPS1, and citrin regulatory regions in the liver, lung, and A549 lung adenocarcinoma cells suggest that all three genes appear to be poised for expression in the lung tissue." (PMID 37047726, 2023). "NAGS and CPS1 had a similar median mRNA expression in lung adenocarcinoma (LUAD, n = 517) and matched normal tissue, while citrin was overexpressed in LUAD." (PMID 37047726, 2023). "Patterns of DNase hypersensitive sites and histone modifications in the upstream regulatory regions of NAGS, CPS1, and citrin genes were similar in liver tissue, lung tissue, and A549 lung adenocarcinoma cells despite different expression levels of the three genes in the liver and lung." (PMID 37047726, 2023).
lung carcinoma (1 paper, 2023). "Although NAGS is expressed in lung cancer derived cell lines, expression of the NAGS gene and its product was not evaluated in tumors with aberrant expression of CPS1 and citrin." (PMID 37047726, 2023).